ZEB1 (zinc finger E-box binding homeobox 1)
Diseases named in the same sentence as ZEB1 in open-access papers (continued):
Sharing a sentence is not in itself a finding about the gene and the disease.
cancer (continued). "Therefore, it is necessary to develop anti‐cancer drugs that inhibit both ZEB1 and ZEB2 simultaneously, because ZEB1/2 are both deeply involved in the malignant differentiation of cancer cells." (PMID 39362647, 2024). "This downregulation activates JAK-STAT signaling and zfh1 (ZEB1 in mammals), which alone was sufficient to induce cancer without driver mutations." (PMID 39239102, 2024). "Zinc finger E-box-binding homeobox 1 (ZEB1) has been demonstrated to be a oncogene in many cancers." (PMID 38481182, 2024). "Moreover, YAP signaling regulates EMT-induced transcription factors such as Snail1/2, Slug, ZEB1 (Zinc Finger E-box-binding Homeobox 1), and Twist in various cancers." (PMID 39595118, 2024). "Recent findings indicate that neddylation, pivotal for cancer cell migration via the PI3K-Akt pathway, when inhibited, upregulates HIF-1α, modulating EMT-activator ZEB1 in various cancer cell lines, underscoring its significant role in cancer progression and metastasis." (PMID 38191508, 2024). "As EGFR-ERK signaling upregulates ZEB1, PRMT1-mediated EGFR upregulation may also contribute to ZEB1 upregulation and ZEB1-mediated cancer stem cell regulation." (PMID 39201539, 2024). "Furthermore, studies have shown that the mesenchymal state is connected with the transcription factor ZEB1, which is a central regulator of lipid metabolism and can promote the stemness, colonization ability, and metabolic adaptability of cancer cells." (PMID 38206305, 2024). "High expression of ZEB1 is related to the poor prognosis of cancer patients." (PMID 39409891, 2024). "NOTCH1 intracellular C-terminal domain (NICD) is a transcriptional regulator which takes part in the highly complex transcriptional network regulating EMT mediators, including Snail, ZEB1, and N-cadherin and its inhibition suppresses cancer progression in different models." (PMID 38398197, 2024). "The expression level of ZEB1 is tightly regulated by miRNAs in cancer." (PMID 38733529, 2024). "since ZEB1 is one of the most frequently activated signals in human cancers, whether malignant crosstalk between these two types of cells triggers additional downstream pathways deserves further exploration." (PMID 38898490, 2024). "And it has also been reported that ZEB1 was abnormally expressed in a variety of human cancers, which could promote cells’ migration, invasion, and metastasis." (PMID 38693503, 2024). "In addition to its role in epithelial-to-mesenchymal transition (EMT) control, the ZEB1 transcription factor is involved in a multitude of biological processes, including cell proliferation, survival, and invasion of cancer cells." (PMID 39736693, 2024). "As ZEB1 involves in proliferation, metastasis and glycolysis of cancer cells, we tried to find out whether PFK-1 could modulate the expression of ZEB1." (PMID 38481182, 2024). "ZEB1 is a key element of a network of transcription factors that endows cancer cells with a pro-invasive and mesenchymal-like phenotype and predicts poor clinical outcomes in a variety of human cancers." (PMID 38183060, 2024). "ZEB1 is a pleiotropic transcription factor frequently expressed in carcinomas." (PMID 38966180, 2024). "IL-6, as an essential trigger of epithelial-to-mesenchymal transition, activates STAT3, followed by transcription of ZEB1 and production of mesenchymal-like proteins and a mesenchymal phenotype, which is utilized by carcinoma cells to promote invasion, angiogenesis, metastasis, and apoptosis." (PMID 38541074, 2024). "Indeed, similarly to carcinomas, Zeb1 is a repressor of E-cadherin expression and promotes dedifferentiation." (PMID 38247872, 2024). "Hence, trapping carcinoma cells in the E/M state, was achieved by Snail overexpression combined with Zeb-1 knockdown." (PMID 38238426, 2024). "ZEB1 drives the EMT by transcriptional suppression of the genes encoding the cell–cell adhesion molecule E-cadherin, and it promotes invasion in many carcinomas." (PMID 39311710, 2024).
cancer (continued). "ZEB1 is a known regulator of cancer EMT (epithelial–mesenchymal transition)." (PMID 37444395, 2023). "A recent study using K-Ras–initiated lung tumors showed that ZEB1-induced EMT is linked to immunotherapy resistance by increasing the expression of PD-L1 and CD47 by cancer cells, and then driving the polarization of adjacent TAMs into immunosuppressive M2 macrophages." (PMID 36823234, 2023). "Therefore, we examined the epithelial‐mesenchymal transition status of cancer cells within both areas around the necrotic foci and far from the necrotic foci, using a ZEB‐1 antibody." (PMID 36127822, 2023). "Although TGF-signalling is associated with cancer suppression in the early stages of tumour development, in late-stage tumours it exerts oncogenic function partially through inducing EMT-related factors such as Snail, Slug, ZEB1, ZEB2 and LEF1." (PMID 37239035, 2023). "Thus, it is possible that ZEB1 represents a mechanism where CM proliferation is sustained by ZEB1 but at some point, mitotic stress is reached forcing the self-limiting DNA damage response to initiate terminal differentiation and avoid cancer." (PMID 36862248, 2023). "Inhibition of miR-200c or high expression of ZEB1 may lead to poor prognosis in various cancers, including breast and ovarian carcinoma." (PMID 38023171, 2023). "It is still unclear whether these diverging roles of ZEB1 in regulating lipid metabolism in macrophages, adipocytes, and cancer cells are mediated by distinct or overlapping mechanisms." (PMID 38097578, 2023). "In that respect, it is relevant to mention that ADNP was recently identified as a binding partner of the ZEB1/NuRD complex (zinc finger E-box-binding homeobox 1/Nucleosome Remodeling and Deacetylase) which is critically involved in epigenetic cancer programming of EMT hallmarks." (PMID 36945042, 2023). "Indeed, ZEB1 deletion in fibroblasts promoted inflammation-driven cancer initiation and progression in a context- and stage disease-dependent manner." (PMID 38124183, 2023). "More functional research clarified that ZEB1 participated in the cell polarity factor and basement membrane synthesis inhibition but promoted the matrix metalloprotease level; therefore, ZEB1 greatly promoted basement membrane remodeling and subsequent cancer cell invasion." (PMID 37124931, 2023). "For instance, the effects of Snai1 and ZEB1 on metastasis can vary depending on the type of cancer." (PMID 37444447, 2023). "Similarly, the up-regulation of neurogenin 3, which is usually repressed by ZEB1, attenuated ZEB1-induced cancer stemness and symmetric CSC division." (PMID 38139138, 2023). "Furthermore, the lncRNA metastasis-associated lung adenocarcinoma transcript 1 (MALAT1), upregulated in various types of cancers, promotes LC proliferation and metastasis by acting as ceRNA for anti-metastatic miR-200a, inducing ZEB1 TF expression." (PMID 37464436, 2023). "Thus, SLFN5 suppresses cancer cell proliferation and induces apoptosis by regulating the ZEB1/PTEN/AKT pathway and purine metabolism." (PMID 37771431, 2023). "The expression of ZEB1 altered predominantly in various cancer types." (PMID 37749132, 2023). "Furthermore, ZEB1 has been suggested to interact directly with the Hippo pathway in cancer cells through YAP." (PMID 36862248, 2023). "Additionally, overexpression of miR-200 has been shown to induce E-cadherin upregulation thereby gaining epithelial characteristics in cancer cells, due to direct targeting of ZEB1/2." (PMID 37655825, 2023). "However, depletion of Zeb1 in a mouse model also reduces phenotypic variability of cancer cells, particular their phenotypic/metabolic plasticity." (PMID 37076857, 2023). "As an activator, ZEB1 forms a complex with YAP1 to promote cancer progression." (PMID 36936987, 2023).
cancer (continued). "Finally, we demonstrated that depletion of hsa_circ_0000228, the most upregulated ZEB1‐circRNA in SF3B1‐mutated MDS, affects mitochondrial functions and interacts with cancer‐related miR‐1248." (PMID 37408496, 2023). "ZEB1 has been extensively characterized for its role promoting a dedifferentiated and stem-like phenotype in cancer cells, but recent evidence indicates that it also promotes cell plasticity in non-malignant cells of multiple tissue origins, including macrophages." (PMID 38097578, 2023). "Thus, the direct interaction between cancer cells and fibroblasts induces upregulation of both ZEB1 and YAP1, which in turn promotes a transcriptional reprogramming towards a more aggressive hybrid EMT phenotype." (PMID 36936987, 2023). "Interestingly, by mining our RNA-Seq data, we found that the Zn2+-bound ZEB1 activates multiple genes relevant to cancer metastasis, including the MMP family, integrin family, and LOX family genes." (PMID 36910659, 2023). "ZEB1 triggers a more motile phenotype in cancer cells, thus increasing their migratory capacity." (PMID 37870961, 2023). "Although the mechanism by which ZEB1 mediates the effect of Metformin to promote an immunosuppressive status in macrophages remains to be elucidated, Metformin inhibits mTORC1, whose genetic and pharmacological ablation upregulates ZEB1 in cancer cells." (PMID 37978290, 2023). "Also, the CAF secretome improves the expression of vimentin, ZEB1, and Snail in cancer cells, which are mesenchymal proteins essential for cancer progression." (PMID 37834441, 2023). "TGF-β can promote EMT of cancer cells by inducing ZEB1 and enhancing GPX4 inhibitor activity." (PMID 38023171, 2023). "Furthermore, VM-forming cancer cell lines UM-UC-3 and J82 exhibited higher zinc finger E-box binding homeobox 1 (ZEB1) expression." (PMID 37052868, 2023). "ZEB1 has a pro-invasive and prometastatic role in carcinomas." (PMID 37870961, 2023). "As a driver of EMT, ZEB1 downregulates canonical epithelial genes (e.g., E-cadherin, occludin) and upregulates mesenchymal markers (e.g., vimentin, fibronectin) in different types of carcinomas." (PMID 37870961, 2023). "From our data we conclude that cancer stem cells may contribute to UM heterogeneity and plasticity and that ZEB1 may play a regulatory role in it." (PMID 35404029, 2022). "In malignant tumors, transcription factors like ZEB1 and ZEB2, SNAI1 and SNAI2, and Twist-related protein (TWIST) 1 and 2 may lead to migratory and invasive cancer cells." (PMID 35463825, 2022). "Thus, our study supplies the evidence for ZEB1 as a bridge between the glycolipid metabolism and mesenchymal cancer cell ferroptosis sensitivity." (PMID 35844792, 2022). "Furthermore, CM-PM increased the expression of the mesenchymal markers Slug, Zeb1, and Zeb2 and reduced the expression of the epithelial marker E-cadherin in cancer cells at both the transcriptional and translational levels." (PMID 36352257, 2022). "In addition, both siRNAs repress the expression of Snail and ZEB1/2 in cancer cells which have high levels of both Snail and ZEB1/2." (PMID 35451213, 2022). "In fact, whether NF-κB/p65 directly binds to the promoter region of ZEB1/2 in cancer cells remains unclear." (PMID 36140527, 2022). "As miR-200 family determines the epithelial phenotype of cancer cells by targeting the E-cadherin repressors ZEB1 and ZEB2 proteins, our results displays that HOTAIR induces the migration and metastasis of GC cells through miR-200 family, thereby affecting EMT." (PMID 34923813, 2022). "Therefore, epigenetic targets are valuable in preventing cancer metastasis through regulation of ZEB1." (PMID 35454770, 2022). "Cancer cells with high levels of ZEB1/2 show low levels of ESRP1/2 and high levels of CD44s." (PMID 36140527, 2022). "BPL2 diminished ZEB1 expression, and it could be assumed that it inhibits cancer cell migration via the same mechanisms." (PMID 36547923, 2022).
cancer (continued). "We suggest that the level of O-GlcNAcylation and ZEB1 may be used as the biomarker to predict the responsiveness of mesenchymal cancer cell to ferroptosis-inducing therapies." (PMID 35844792, 2022). "We next examined whether siEts1/2 suppressed both Snail and ZEB1/2, both of which were constitutively expressed in cancer cells." (PMID 35451213, 2022). "We found that the number of spheroids formed from the single-cell suspension culture and the expression of the stemness genes were both negatively correlated with the ZEB1 expression level, suggesting that ZEB1 may suppress cancer stem cell properties in UM." (PMID 35404029, 2022). "Moreover, various CHK1 inhibitors have been tested in anti-cancer clinical trials and warrant investigation as candidate radiosensitising agents for breast tumours with high levels of ZEB1." (PMID 36499447, 2022). "Usually, ZEB1 facilitates cancer progression by inhibiting its target gene transcription." (PMID 36273188, 2022). "The NF-κΒ/ZEB1 pathway has been found to repress E-cadherin expression in cancer cell lines." (PMID 36293154, 2022). "Importantly, members of the Ets transcription factor family, Ets1 and Ets2, contribute to the upregulation of both Snail and ZEB1/2 in cancer cells." (PMID 35451213, 2022). "Additionally, ZEB1 is a transcriptional activator, or, has repressor functions in normal regulatory processes and dysregulated progress, such as cancer progression and metastasis." (PMID 36499447, 2022). "Indeed, YAP and/or TAZ have the ability to interact with SNAIL, SLUG, and/or ZEB1 during development or cancer progression, whereas LATS1/2 also regulate chromosomal instability." (PMID 35859006, 2022). "Therefore, sustained high expression of ZEB1/2 in cancer cells is highly dependent on the ERK and NF-κB pathways." (PMID 36140527, 2022). "In this study, we hypothesized that Ets1 contributes to the upregulation of Snail and ZEB1/2 in cancer cells." (PMID 35451213, 2022). "Likewise, Zeb-1, which was highly expressed in a cancer stem cell (CSC) subpopulation of MCL cells, induced lipid accumulation and correlated with BTZ resistance in MCL cells." (PMID 36430955, 2022). "Furthermore, compared to the ZEB1 wide type cells, ZEB1-S555A mutant cancer cells displayed the increased cell viability and decreased the levels of MDA in the presence of Erastin under the glucose cultured condition." (PMID 35844792, 2022). "Snail induction by TGF‐β and active Ras is dramatically inhibited using siRNAs against both Ets1 and Ets2 together, but not on their own; in addition, siRNAs against both Ets1 and Ets2 also downregulate the constitutive expression of Snail and ZEB1/2 in cancer cells." (PMID 35451213, 2022). "Tumorigenicity and invasiveness are important acquired characteristics for the development and progression of cancer, and could be regulated by transcription factors associated with EMT, such as ZEB1, ZEB2, SNAI1, SLUG, and STAT3." (PMID 35723302, 2022). "Twist and Zeb1 genes help epithelial–mesenchymal transition (EMT) in cancer cells." (PMID 36080307, 2022). "Importantly, Ets1/2 regulates both representative EMT regulators of Snail and ZEB1/2 in cancer cells." (PMID 35451213, 2022). "Furthermore, as an EMT activator, ZEB1 plays a key role in cell plasticity and promotes metastasis of cancers." (PMID 35982471, 2022). "ZEB1 is a prime transcription factor that initiates EMT in cancer cells." (PMID 36302751, 2022). "Together, our data suggest the presence of important interplay between the endogenous metabolic dysregulation and development of an immunosuppressive TME through a Zeb1-dependent mechanism, highlighting the possibility of identifying new targets and therapeutic strategies for cancer treatment." (PMID 35246504, 2022). "The pathological roles of SNAIL and ZEB1/2 are still controversial during cancer progression." (PMID 36140527, 2022).